CD248 (CD248 molecule)
Diseases named in the same sentence as CD248 in open-access papers (continued):
Sharing a sentence is not in itself a finding about the gene and the disease.
neuroblastoma (11 papers, 2017 to 2025). Neuroblastoma (NB) is the most common solid, extracranial childhood tumor. "CD248 expression levels were closely associated with tumor grade, invasiveness, and poor prognosis in breast cancer and neuroblastoma." (PMID 33748448, 2021). "111In labeled scFv78-Fc was generated to specifically target CD248-positive Ewing sarcoma and neuroblastoma in tumor-bearing mice." (PMID 40276611, 2025). "Beyond that, scFv-CM6-DM1-liposome, an antibody-drug-conjugated immunoliposome, was generated to target CD248-overexpressing human neuroblastoma cells and enhance drug efficacy." (PMID 40276611, 2025). "Significant CD248 mRNA expression was found in IMR-32 neuroblastoma cells and in human fetal foreskin fibroblast (HFFF) cell cultures, a model of skin-derived MSCs." (PMID 37298499, 2023). "Consistent with this hypothesis, when CD248 is treated with O‐glycanase and sialase, its molecular weight is reduced from 165 to 95 kDa when purified from human neuroblastoma cells." (PMID 31287944, 2019). "Human neuroblastoma xenograft tumors were positive for CD248 suggesting that CD248 may be a therapeutic target for neuroblastoma." (PMID 30847027, 2019). "Other cell lines, such as 55N (neuroblastoma), Jurkat (T cells), and Akata (B cells), did not express CD248." (PMID 37298499, 2023). "A fully human anti-CD248 bound to human A-673 Ewing sarcoma cells and SK-N-AS neuroblastoma cells but not HT-1080 fibrosarcoma cells." (PMID 30847027, 2019).
renal fibrosis (11 papers, 2015 to 2026). A final common manifestation of a wide variety of chronic kidney diseases characterized by glomerulosclerosis and tubulointerstitial fibrosis. "By parabiosis of GFP reporter mice and Cd248–/– mice, we showed that attenuation of renal fibrosis was associated with a decrease of macrophage infiltration in Cd248–/– mice." (PMID 33033277, 2020). "In the present study, we demonstrate a pathogenic role for CD248 in the development of renal fibrosis." (PMID 26633297, 2015). "Gene deficiency of CD248 has been reported to inhibit microvascular thinning and renal fibrosis." (PMID 41382249, 2025). "We show that CD248-deficient mice are protected from renal fibrosis and microvascular rarefaction." (PMID 26633297, 2015). "We thus hypothesised that CD248-expressing stromal cells are pathogenic in renal fibrosis." (PMID 26633297, 2015). "CD248 has been demonstrated to be upregulated in cancers, tumors and many fibrotic diseases in human and mice, such as liver damage, pulmonary fibrosis, renal fibrosis, arthritis and tumor neovascularization." (PMID 36119065, 2022). "Picrosirius red staining showed attenuation of renal fibrosis in the UUO kidneys of mice following Cd248-TT vaccination." (PMID 33033277, 2020). "In the second renal fibrosis model induced by unilateral ischemia–reperfusion injury (uIRI), Cd248 disruption resulted in reduced collagen deposition and fibrosis, too." (PMID 33033277, 2020). "CD248 involvement in tissue fibrosis was first examined in a renal fibrosis model induced by unilateral ureteral obstruction (UUO)." (PMID 33033277, 2020). "Because galectin-3 plays a significant role in the activation of M2 macrophages and UUO-induced renal fibrosis, we were intrigued about the interaction between galectin-3 and CD248 in renal fibrosis." (PMID 33033277, 2020). "In standard renal fibrosis models, CD248 knockout mice were protected from fibrosis and microvascular rarefaction due to a stabilizing effect of pericytes with less migration and differentiation of pericytes toward a myofibroblast phenotype." (PMID 30847027, 2019). "On the contrary, CD248−/− mice were protected from renal fibrosis and capillary rarefaction, probably inhibiting pericyte differentiation toward α-SMA+ interstitial myofibroblasts and preventing vascular instability and collagen production." (PMID 30285896, 2018). "CD248-expressing fibroblasts have also been identified in hepatic and renal fibrosis, representing a reparative population." (PMID 28122639, 2017). "With progressive renal fibrosis, upregulated expression of CD248 was observed within the stromal cell compartment of the kidney." (PMID 26633297, 2015). "Using the unilateral ureteral obstruction (UUO) model of renal fibrosis, we investigated the effect of genetic deletion of CD248 on post obstructive kidney fibrosis." (PMID 26633297, 2015). "We demonstrate that CD248-/- mice are protected against myofibroblast accumulation, microvascular rarefaction and renal fibrosis." (PMID 26633297, 2015). "To determine if CD248-/- mice were protected from renal fibrosis as a result of a change in leucocyte accumulation within the tissue, we examined the numbers of CD45, CD3 and F4/80 expressing leucocytes in kidney tissue using confocal microscopy." (PMID 26633297, 2015). "Targeting CD248 expressing stromal cells has the capability to modulate both microvascular rarefaction and tissue fibrosis, 2 vital disease processes in progressive renal fibrosis." (PMID 26633297, 2015). "This suggests that CD248 may be involved in the development of DN renal fibrosis through TGF-β1/Smad pathway." (PMID 41382249, 2025). "This suggests that VER or NBIF may be involved in inhibiting the progression of renal fibrosis in DN by regulating the CD248/TGF-β/Smad axis." (PMID 41382249, 2025). "CD248, as a type I transmembrane glycoprotein, is up-regulated in mouse models of renal fibrosis." (PMID 41382249, 2025).
renal fibrosis (continued). "CD248 is also identified as a pivotal stromal cell marker in renal allograft rejection, associated with HIF-1α and IL-1β pathways (also two pivotal pathways in renal fibrosis of DN)." (PMID 41382249, 2025). "In addition, CD248 is also involved in renal fibrosis, pulmonary fibrosis, arthritis, and tumor neovascularization, and has become a potential target for the treatment of these diseases." (PMID 36119065, 2022). "We hypothesized that vaccination with Cd248 cDNA fused to the C fragment of tetanus toxoid (Cd248-TT) would confer adaptive immunity targeting kidney myofibroblasts and thereby attenuate renal fibrosis." (PMID 33033277, 2020). "Thus, CD248 stromal cells have a role in renal fibrosis, furthermore, targeting CD248 was effective at inhibiting both microvascular rarefaction and renal fibrosis through modulation of pericyte and stromal cell function." (PMID 30847027, 2019). "To test our hypothesis, we have induced renal fibrosis using the unilateral ureteral obstruction (UUO) model of kidney injury in CD248-/- mice." (PMID 26633297, 2015). "As CD248 was found to be highly expressed by a subpopulation of pericytes during inflammation, we next determined whether CD248-/- mice were protected from renal fibrosis as a result of having less tissue myofibroblasts." (PMID 26633297, 2015). "To examine the role of CD248 in renal fibrosis, we performed UUO in CD248-/- mice." (PMID 26633297, 2015). "However, the function and mechanism of CD248 in renal fibrosis and EMT of DN remain largely unknown." (PMID 41382249, 2025). "Thus, CD248 vaccination attenuated renal fibrosis effectively." (PMID 33033277, 2020). "CD248 participates in HG-induced EMT of renal tubular epithelial cells and renal fibrosis by regulating TGF-β1/Smads pathway, and VER and NBIF are two potential natural drugs which targets it to ameliorate DN." (PMID 41382249, 2025). "Taken together, these data indicate that myofibroblast CD248 induced pro-fibrotic phenotype switching of macrophages through galectin-3, and that macrophage CCL17 upregulated collagen expression of myofibroblasts thereby leading to renal fibrosis." (PMID 33033277, 2020). "Furthermore, in an experimental model of liver fibrosis, the total liver mRNA of collagen and α-SMA was reduced in CD248-deficient mice compared with wild-type mice, and in a model of renal fibrosis, no increase of α-SMA molecule was observed in CD248-deficient mice." (PMID 30285896, 2018).
colorectal cancer (10 papers, 2014 to 2025). A primary or metastatic malignant neoplasm that affects the colon or rectum. "The expression of CD248 and pathway-associated proteins was examined for association with 5-year disease-specific survival of a colorectal cancer cohort divided into training and validation sets." (PMID 30847027, 2019). "However, a marked decrease in tumour growth, metastasis and invasion was observed when CD248 deficient mice were challenged with human colorectal cancer xenografts." (PMID 31287944, 2019). "Interest in endosialin (CD248) stemmed from the demonstration that it was the most highly upregulated transcript in colorectal cancer tumour vasculature, compared to the vasculature of normal adjacent tissue." (PMID 27434038, 2016). "CD248 is expressed in fibroblasts and pericytes of colorectal cancer." (PMID 30847027, 2019).
Arthritis (9 papers, 2011 to 2024). Inflammation of a joint. "The aim of our study was to investigate the role of CD248 expression by MSCs in the pathology of proliferative and invasive remodeling of synovial tissue in arthritis." (PMID 37298499, 2023). "These CD248-dependent alterations serve to reduce leukocyte infiltration, synovial fibroblast migration, proliferation and inflammation in arthritis." (PMID 21549007, 2011). "We recently showed that the cytoplasmic domain of CD248 is important in facilitating an inflammatory response in a mouse model of arthritis." (PMID 21549007, 2011). "In an effort to determine the inflammatory effectors which modulate CD248 expression, we treated two different models of MSCs (skin and synovial tissue) in vitro with a range of growth factors and cytokines that have been identified as perpetrators of the pathology of cancer and arthritis." (PMID 37298499, 2023). "In humans, studies have confirmed that CD248 and PPDN (together with FAP and DAF/CD55) are highly expressed in the synovial tissue in the early stage of arthritis." (PMID 37298499, 2023). "Synovial tissue expression of stromal markers in early arthritis was analyzed using immunofluorescence to detect stromal markers CD55, CD248, fibroblast activation protein and podoplanin." (PMID 30847027, 2019). "Stromal cell markers CD55, CD248, FAP and podoplanin are expressed in the earliest stage of arthritis." (PMID 30847027, 2019). "Stromal cell markers CD55, CD248, FAP and podoplanin are expressed in ST in the earliest stage of arthritis." (PMID 28793332, 2017). "CD248 knockout mice and mice lacking the cytoplasmic domain of CD248 both showed reductions in experimental arthritis compared to wild‐type animals, and displayed a marked reduction in synovial inflammation." (PMID 31287944, 2019). "CD248 knockout (CD248KO/KO) and CD248 cytoplasmic domain lacking (CD248CyD/CyD) mice had less severe arthritis, with lower plasma levels of proinflammatory cytokines than controls." (PMID 30847027, 2019). "In an experimental model of rheumatoid arthritis, we recently determined that CD248KO/KO mice and mice lacking the cytoplasmic domain of CD248 (CD248CyD/CyD mice) develop less severe arthritis than CD248WT/WT mice, the differential response likely due to alterations in synovial fibroblast function." (PMID 21549007, 2011). "ST from 56 patients included in two different early arthritis cohorts and 7 non-inflammatory controls was analysed using immunofluorescence to detect stromal markers CD55, CD248, fibroblast activation protein (FAP) and podoplanin." (PMID 28793332, 2017).
hepatocellular carcinoma (8 papers, 2019 to 2025). A malignant tumor that arises from hepatocytes. "CD248 expression in cancer-associated fibroblasts promotes hepatocellular carcinoma progression through interaction with CD68 on macrophages and consequent polarization to the tumor-promoting M2 phenotype." (PMID 36401329, 2022). "In addition, CD248 upregulation is associated with poor prognosis of renal cell carcinoma, urothelial carcinoma, hepatocellular carcinoma, colorectal cancer, and so on." (PMID 40276611, 2025). "Studies have confirmed that CD248 was overexpressed in CAFs of hepatocellular carcinoma (HCC), which promoted the polarization of tumor-associated macrophages (TAMs) to the M2 phenotype, an inhibitory maker in TME, by regulating growth arrest-specific protein 6 (GAS6)." (PMID 34970489, 2021). "Genetic inactivation of CD248 resulted in accelerated tumor growth in an inducible mouse hepatocellular carcinoma model." (PMID 30847027, 2019). "Histological analysis of human hepatocellular carcinoma samples indicated an inverse correlation between tumor cell proliferation and stromal CD248 expression." (PMID 30847027, 2019). "Thus, CD248-expressing hepatic stellate cells are a negative regulator of hepatocellular carcinoma progression." (PMID 30847027, 2019). "In our previous study, we found that PSMA and CD248 were both expressed specifically in the vasculature in hepatocellular carcinoma (HCC), and vascular-expressed PSMA and CD248 might be used as prognostic markers and vascular therapeutic targets for HCC." (PMID 34869004, 2021). "The targeting of CD248 may even be detrimental in some tumour types, as CD248 expression upregulated in hepatocellular carcinoma (HCC) patients in hepatic stellate cells (specialised pericytes found in the liver vasculature) was found to be protective correlating with better outcomes." (PMID 31287944, 2019).
liver fibrosis (8 papers, 2016 to 2024). "It was discovered that the HIF signaling pathway controlled the expression of CD248/endosialin, causing the onset of liver fibrosis caused by BCS." (PMID 36523459, 2022). "Similar to fibrosis in kidney, CD248 deficiency also protected mice against liver fibrosis following liver injury, and these KO mice displayed reductions in collagen but no change in inflammation." (PMID 31287944, 2019). "Having established that CD248 expression is restricted to HSCs and myofibroblasts, we sought to determine the functional significance of CD248 in the generation of liver fibrosis using a CD248-deficient murine model." (PMID 26078290, 2016). "Our data show that deletion of CD248 reduces susceptibility to liver fibrosis via an effect on PDGF signalling, making it an attractive clinical target for the treatment of liver injury." (PMID 26078290, 2016). "To determine CD248 expression in liver fibrosis, we performed Sirius red and IHC staining for CD248 in the tissue array, which contained 40 cirrhotic liver tissues and 9 healthy controls." (PMID 35317721, 2022). "The results showed CD248 expression was significantly increased in human cirrhotic livers (p < 0.001) and the CD248 staining level correlated positively with the severity of liver fibrosis (p < 0.0001)." (PMID 35317721, 2022). "CD248 expression was examined in patients with liver cirrhosis and in mice with CCl4-induced liver fibrosis." (PMID 35317721, 2022). "CD248 expression was also detected in human samples of liver fibrosis on myofibroblasts and perivascular cells and was elevated in human liver fibrosis samples compared to healthy controls as well as correlating with levels of collagen deposition." (PMID 31287944, 2019). "Hepatic fibrosis was induced in CD248 knockout mice and control mice with carbon tetrachloride treatment." (PMID 30847027, 2019). "CD248 expressed in the liver by stellate cells and portal fibroblasts, was upregulated in liver fibrosis." (PMID 30847027, 2019). "Herein, we demonstrate that CD248 expression is upregulated in hepatic fibrosis where its expression is confined to HSCs and myofibroblasts." (PMID 26078290, 2016). "Hepatic fibrosis was induced in CD248−/− and wild-type controls with carbon tetrachloride (CCl4) treatment." (PMID 26078290, 2016). "The distribution of CD248+ cells was similar in CCl4-induced liver fibrosis, again being localised to the sinusoids and blood vessels." (PMID 26078290, 2016). "The restricted expression of CD248 in HSCs and myofibroblasts and the temporal regulation during disease makes CD248 an attractive target for the modulation of liver fibrosis." (PMID 26078290, 2016). "Digital morphometric analysis of PSR sections demonstrated a marked reduction in liver fibrosis in CD248−/− mice compared with WT mice at both 8 (56.4% reduction; p<0.0001) and 12 weeks (51.1% reduction; p<0.05), respectively." (PMID 26078290, 2016). "In this article, we demonstrate for the first time that CD248 is a major regulator of liver fibrosis in response to chronic injury, which is upregulated in liver fibrosis in both human and mouse settings." (PMID 26078290, 2016). "A similar pattern was observed in chronic CCl4-induced liver fibrosis in mouse liver where CD248 expression also appeared higher (1.6-fold difference; p=0.09) than in uninjured mouse liver." (PMID 26078290, 2016). "In summary, our study demonstrated that CD248 was specifically expressed on activated hepatic stellate cells in liver fibrosis and CD248 could be used as an effective target for anti-fibrotic therapy." (PMID 35317721, 2022). "To explore whether specific killing of myofibroblasts could effectively alleviate liver fibrosis, we first expressed and purified the fully human antibody IgG78, which specifically recognizes CD248." (PMID 35317721, 2022). "CD248 was mainly expressed on α-SMA+ myofibroblasts in liver fibrosis." (PMID 35317721, 2022).